PIEZO2 (piezo type mechanosensitive ion channel component 2)
Diseases named in the same sentence as PIEZO2 in open-access papers (continued):
Sharing a sentence is not in itself a finding about the gene and the disease.
chronic obstructive pulmonary disease (3 papers, 2021 to 2022). A chronic and progressive lung disorder characterized by the loss of elasticity of the bronchial tree and the air sacs, destruction of the air sacs wall, thickening of the bronchial wall, and mucous accumulation in the bronchial tree. "Human Piezo2 defects and Piezo2 gain-of-function mutations are associated with respiratory insufficiency at birth, chronic obstructive pulmonary disease, and adult sleep apnea." (PMID 35154133, 2022). "Interestingly, gain-of-function mutations in Piezo2 and Piezo2 deficiency in humans have been associated with respiratory diseases, including respiratory insufficiency at birth, chronic obstructive pulmonary disease, and sleep apnea in adults." (PMID 33422128, 2021). "Moreover, abnormal activation of Piezo2 might be related to the occurrence of chronic pulmonary obstructive disease (COPD), in which the Hering-Breuer reflex is impaired." (PMID 35906615, 2022).
diabetic neuropathy (3 papers, 2021 to 2024). A chronic, pathological complication associated with diabetes mellitus, where nerve damages are incurred due to diabetic microvascular injury involving small blood vessels that supply these nerves, resulting in peripheral and/or autonomic nerve dysfunction. "We used immunohistochemistry associated with a battery of antibodies to identify the axon and Schwann related cells (since both are involved in diabetic neuropathy) and a series of putative mechanoproteins (PIEZO2, ASIC2 and TRPV4) which are involved in mechanotransduction." (PMID 34640627, 2021).
distal arthrogryposis type 5 (3 papers, 2015 to 2024). "Overall, we used C. elegans to study the pathophysiological effect of an ortholog of human PIEZO2 mutation causing distal arthrogryposis type 5 (DA5) and identified the putative suppressor gex-3(L353F)." (PMID 38349741, 2024).
Hip dysplasia (3 papers, 2020 to 2026). The presence of developmental dysplasia of the hip. "In addition, the elimination of Piezo2 in proprioceptive neurons in mice caused skeletal abnormalities that manifested as hip dysplasia and spine malalignment, which were also observed in individuals with PIEZO2 deficiency syndrome." (PMID 40781923, 2026). "Furthermore, human PIEZO2 deficiency results in proprioception defects and hip dysplasia." (PMID 39715266, 2024). "However, while the loss of Piezo2 in proprioceptive neurons successfully recapitulated spine malalignment and hip dysplasia, the cause for other phenotypes like hand contracture remains unknown." (PMID 32576830, 2020). "While loss of Piezo2 in chondrogenic or osteogenic lineages does not lead to human-like skeletal abnormalities, its loss in proprioceptive neurons leads to spine malalignment and hip dysplasia." (PMID 32576830, 2020). "Deletion of Piezo2 in proprioceptive neurons (Pvalb-Cre:Piezo2f/f) but not in osteogenic (Col1a-Cre:Piezo2f/f) or chondrogenic (Col2a-Cre:Piezo2f/f) cells resulted in skeletal defects, including spine malalignment and hip dysplasia." (PMID 39715266, 2024).
itch (3 papers, 2022 to 2023). "The question remains as to why PIEZO1 transduces mechanical itch when PIEZO2 is expressed in somatosensory neurons and is exquisitely sensitive to mechanical stimuli." (PMID 35732741, 2022).
non-small cell lung carcinoma (3 papers, 2022). A group of at least three distinct histological types of lung cancer, including non-small cell squamous cell carcinoma, adenocarcinoma, and large cell carcinoma. "In contrast, a study has shown that Piezo2 expression levels were downregulated in non-small cell lung cancer (NSCLC) compared with normal tissues." (PMID 35991548, 2022). "Interestingly, both Piezo1 and Piezo2 are downregulated in non-small cell lung cancer (NSCLC) tumor tissue compared to matched adjacent normal tissue." (PMID 36158191, 2022). "Subsequent functional experiments showed that loss of Piezo2 could enhance the biological behavior of tumor cells including migration and proliferation ability, which suggested that Piezo2 may play an inhibitory function in tumor progression of non-small cell lung cancer (NSCLC)." (PMID 35991548, 2022). "The mRNA expression of Piezo1 and Piezo2 is significantly lower in tumor tissues of non-small cell lung cancer (NSCLC) than in neighboring nontumor tissues." (PMID 36615408, 2022).
osteoporosis (3 papers, 2022 to 2024). A condition of reduced bone mass, with decreased cortical thickness and a decrease in the number and size of the trabeculae of cancellous bone (but normal chemical composition), resulting in increased fracture incidence. "Deletion of Piezo1 or Piezo2 in osteoblast or osteoclast lineage cells causes a severe osteoporosis phenotype with numerous spontaneous fractures, specifically in osteoblast lineage cells, indicating that Piezo1 and Piezo2 are important in bone formation and bone function." (PMID 38956429, 2024). "In summary, these persistent ASIC-like currents are suggested to be evoked in osteoporosis as well and sustained by the subthreshold-imbalanced Piezo Ca2+ currents due to the Piezo2 microinjury-derived “leakiness”." (PMID 36012312, 2022).
pulmonary hypertension (3 papers, 2023 to 2025). Increased pressure within the pulmonary circulation due to lung or heart disorder. "There is no robust evidence indicating the role of Piezo2 in VILI, although Piezo2 is considered an MSIC, and the impairment of Piezo2 is associated with sleep apnea and pulmonary hypertension." (PMID 39664395, 2024). "A recent study showed lung EC lacking Piezo2 expression were impaired in NO production, endothelial mesenchymal transition, and develop pulmonary hypertension." (PMID 36672270, 2023).
Alzheimer disease (2 papers, 2025 to 2026). A progressive, neurodegenerative disease characterized by loss of function and death of nerve cells in several areas of the brain leading to loss of cognitive function such as memory and language. "Accordingly, the irreversible Piezo2 channelopathy-induced loss of the Piezo2-initiated ultradian prefrontal-hippocampal axis leads to Alzheimer's disease pathophysiology onset." (PMID 40806339, 2025). "In replication analyses, 21 genes showed nominal support in UK Biobank and Alzheimer's Disease Genetics Consortium (ADGC) cohorts, with eight genes (TREM2, ACADS, MFSD12, NUP210L, PIEZO2, PSEN1, SMURF2, AKAP13) supported under identical masks." (PMID 41960309, 2026).
Apnea (2 papers, 2019 to 2026). Lack of breathing with no movement of the respiratory muscles and no exchange of air in the lungs. "Contrastingly, optogenetic stimulation of Piezo2+ vagal sensory neurons triggered apnea in adult mice, while mice with ablation of Piezo2 in sensory neurons exhibit aberrant neuronal signalling during lung inflation, impaired Heringg‐Breuer mechanoreflex and increased resting tidal volume." (PMID 40781923, 2026).
arthrogryposis (2 papers, 2018 to 2025). A rare, non-progressive congenital disorder characterized by multiple joint contractures which are present at birth. "Our study presents Chinese patients carrying a missense mutation p.R2718Q in PIEZO2 for the first time who have mild arthrogryposis without other manifestations." (PMID 30285720, 2018). "The patients of Family 2 carrying the mutation p.R2718Q in PIEZO2 have mild arthrogryposis without other manifestations." (PMID 30285720, 2018).
autoimmune conditions (2 papers, 2023 to 2024). "Piezo2 has a central role in sensory processes, and its theorized excessive mechanotransduction-derived non-contact microinjury could lead to a wide array of diseases, including even autoimmune conditions." (PMID 37445856, 2023).
colitis (2 papers, 2023 to 2026). Inflammation of the colon. "Colitis significantly activated CHRNA3+ nociceptors via the NGF-TrkA/pERK/PIEZO2 pathway, converting them from mechanoinsensitive to mechanosensitive." (PMID 42157236, 2026). "Since Piezo2 conditional deletion from nociceptors did not affect colonic mechanical sensitivity in healthy male mice, we measured colonic mechanical sensitivity in male Piezo2wt and Piezo2cKO mice following induction of colonic inflammation." (PMID 37061508, 2023).
colon cancer (2 papers, 2022 to 2025). "PIEZO2 knockdown suppresses proliferation, migration, and invasion while promoting apoptosis in colon cancer cells." (PMID 41327436, 2025). "Functional studies demonstrate that PIEZO2 enhances colon cancer cell proliferation, migration, and invasion through activation of the SLIT2/ROBO1/VEGFC signaling axis." (PMID 41327436, 2025). "Immunohistochemical analyses reveal that PIEZO2-positive staining is markedly stronger in colon cancer tissues than in normal counterparts." (PMID 41327436, 2025).
cystitis (2 papers, 2021 to 2023). Inflammation of the urinary bladder. "CYP-induced cystitis was associated with Piezo2 upregulation in bladder afferent neurons at the mRNA, protein, and functional levels." (PMID 37227654, 2023). "One of our important findings is that CYP-induced cystitis is associated with the upregulation of Piezo2 expression and function in bladder primary afferents." (PMID 37227654, 2023). "In a cyclophosphamide (CYP) model of cystitis, we found that the gene expression of several candidate MSCs (Trpv1, Trpv4, Piezo1, and Piezo2) were all upregulated in the urothelium and detrusor following chronic CYP-induced cystitis, but not acute CYP-induced cystitis." (PMID 35295484, 2021). "Our results suggest upregulation of Piezo2 channels is involved in the development of bladder mechanical allodynia and bladder hyperactivity in CYP-induced cystitis." (PMID 37227654, 2023). "Our results suggest that upregulation of Piezo2 channels is involved in the development of mechanical allodynia and bladder hyperactivity in CYP-induced cystitis." (PMID 37227654, 2023). "We found that several MSC genes including Trpv1, Trpv4, Piezo1, and Piezo2 were all upregulated in both layers of the bladder (urothelium and detrusor), following chronic CYP-induced cystitis, but not acute CYP-induced cystitis." (PMID 35295484, 2021).
depression (2 papers, 2020 to 2022). "Examining significant genes that overlap between the current GWAS of non-anxiety depression and the depression studies revealed putative associations with PIEZO2 and CFAP61." (PMID 35730328, 2022). "Several genes that are nearly adjacent to PIEZO2 and CFAP61 have been implicated in depression." (PMID 35730328, 2022). "To date, neither PIEZO2 nor CFAP61 has been reported to cause a phenotype related to depression." (PMID 35730328, 2022).
glaucoma (2 papers, 2021 to 2025). Increased pressure in the eyeball due to obstruction of the outflow of aqueous humor. "Piezo2 mRNA was expressed in the astrocytes of the optic nerve head, and its expression level was higher in glaucoma model mice." (PMID 33935792, 2021). "Notably, studies have reported the expression of Piezo1 and Piezo2 in the astrocytes of the mouse ONH, with elevated levels of Piezo2 observed in rodent glaucoma model, specifically DBA/2J." (PMID 40873759, 2025).
glomerulosclerosis (2 papers, 2025 to 2026). A hardening of the kidney glomerulus caused by scarring of the blood vessels. "The PIEZO2 gene was reported to mediate the formation of glomerular fibronectin, which results in glomerulosclerosis and development of DN in the mice model." (PMID 40572705, 2025).
intestinal obstruction (2 papers, 2023 to 2025). Blockage of the normal flow of the intestinal contents within the bowel. "Hu Hongzhen’s research group found that Piezo2 channel is involved in visceral pain hypersensitivity caused by IBS and intestinal obstruction." (PMID 40660305, 2025).
lymphedema (2 papers, 2025). Excess fluid collection in tissues, causing swelling. "Higher expression levels of COL1A2, PIEZO2, and POSTN were observed in the keloid group compared with the lymphedema group." (PMID 40742741, 2025).
Merkel Cell Carcinoma (2 papers, 2022 to 2023). "Here, we report that PIEZO2 activity is reduced in Ube3a deficient male and female mouse sensory neurons, a human Merkel cell carcinoma cell line and female human iPSC-derived sensory neurons with UBE3A knock-down, and de-identified stem cell-derived neurons from individuals with AS." (PMID 36859399, 2023). "The role of PIEZO2 in Merkel cell carcinoma is still unknown, but it could be related with the mechanical regulation of the tumor biology or be a mere vestige of the Merkel cell derivation." (PMID 35743679, 2022).
neuroblastoma (2 papers, 2016 to 2023). Neuroblastoma (NB) is the most common solid, extracranial childhood tumor. "Piezo2 protein, encoded by Piezo2/FAM38B genes, was initially identified as mechanically activated (MA) ion channels in the murine neuroblastoma cell line N2A." (PMID 27329839, 2016).
ophthalmoplegia (2 papers, 2018 to 2025). Weakness or paralysis of at least one of the muscles controlling the movement of the eye. "Heterozygous gain-of-function (GoF) mutations in PIEZO2 have been reported in MWKS, DA3, DA5, which typically involve congenital contractures of hands and feet, or cleft palate, ophthalmoplegia, ptosis, and cerebellar malformations." (PMID 30285720, 2018).
psoriasis (2 papers, 2022 to 2023). An autoimmune condition characterized by red, well-delineated plaques with silvery scales that are usually on the extensor surfaces and scalp. "In summary, impaired Piezo2–Piezo1 communication due to the chronically impaired functionality of microdamaged Piezo2 somatosensory terminals in Merkel cell–neurite complexes in psoriasis may ignite the uncontrolled proliferation and differentiation of sensitized keratinocytes, explained later." (PMID 36233237, 2022). "This opinion article will demonstrate the potential relevance of the somatosensory Piezo2 microinjury-induced quad-phasic non-contact injury model in psoriasis through a multidisciplinary approach." (PMID 36233237, 2022).
Trichinella spiralis infection (2 papers, 2022 to 2024). "provided the evidence that expression of Piezo2 in the colon is significantly correlated with the visceral sensitivity in PI-IBS model mice induced via a Trichinella spiralis infection." (PMID 35865309, 2022). "Piezo2 expression in the colon epithelial cells was significantly correlated with visceral sensitivity in post-infectious IBS (PI-IBS) model mice induced via a Trichinella spiralis infection, which indicated that Piezo2 is a potential biomarker for visceral hypersensitivity in IBS." (PMID 39062518, 2024).
adenoma (1 paper, 2024). A neoplasm arising from the epithelium. "In patient samples, adenoma patients exhibited increased expression of genes associated with the tumor immune microenvironment, such as IL6ST, collagen family members, and CRC transition markers, such as GLI3 and PIEZO2, in CARD11+ adenoma patients." (PMID 39408697, 2024).
adenomyosis (1 paper, 2026). The growth of endometrial tissue inside the muscular wall of the uterine corpus. "Consistent with the human data, mice with induced adenomyosis exhibited reduced Piezo1 and eNos staining and elevated Piezo2 and Otr staining in myometrium, concordant with increased fibrosis." (PMID 41836349, 2026).
allergic asthma (1 paper, 2024). A asthma with a basis in a pathological type I hypersensitivity reaction. "Therefore, Piezo2 might be involved mainly in overinflation of lung owing to the impaired Hering-Breuer reflex, premature neonatal death, ARDS, allergic asthma, and obstructive sleep apnea syndrome." (PMID 39664395, 2024).
arthrogryposis syndrome (1 paper, 2021). "PIEZO2 mutations in humans lead to disease of variable clinical phenotypes with overlapping clinical features including arthrogryposis syndrome." (PMID 34324503, 2021).
brain tumors (1 paper, 2023). "This suggests that inhibition of Piezo2 channels in MB cells may have a therapeutic effect by disrupting BTB and increasing the uptake of chemotherapeutic agents in brain tumors." (PMID 37366640, 2023). "A recent groundbreaking study published in neuron identified an important role for Piezo2 in MB cells, where it controls the permeability of the blood–tumor barrier (BTB), which prevents the efficient delivery of drugs that would otherwise be effective against brain tumors." (PMID 37366640, 2023).
cartilage disease (1 paper, 2026). Softening and degeneration of the CARTILAGE. "Specifically, Piezo2‐mediated Ca2+ signalling was only evoked in response to injurious levels (18%) of the strain, which was inhibited by Piezo2 knockdown, suggesting its potential role in cartilage disease induced by hyperphysiological and injurious loadings." (PMID 40781923, 2026).
chronic heart failure (1 paper, 2023). "LF monitoring could gain importance in these special instances, e.g., in eccentric training in chronic heart failure, because it was recently proposed that Piezo2 in proprioceptors could go through pathological hyperexcitation, resulting in autonomic imbalance." (PMID 37108199, 2023).
cognitive decline (1 paper, 2026). "In addition, aging and tooth loss lead to Piezo2 downregulation and neuronal death, potentially resulting in masticatory dysfunction and cognitive decline." (PMID 41884172, 2026).
colorectal adenoma (1 paper, 2024). An adenoma that arises from the colon or rectum. "Genes related to CARD11 overexpression in colorectal adenoma patients included IL6ST, GLI3, and PIEZO2, as well as the collagen-related gene family, whilst MAPK8IP2 gene expression was dramatically elevated in CARD11+ carcinoma patients." (PMID 39408697, 2024).
Constipation (1 paper, 2023). Infrequent or difficult evacuation of feces. "To confirm the effect of Piezo2 deficiency on rectum motility, we reasoned that an even larger bead (4 mm) would cause a more pronounced motility delay in Piezo2SNS mice and additionally mimic impacted stools presented in humans who experience constipation." (PMID 37541196, 2023).
developmental and epileptic encephalopathy (1 paper, 2025). An epilepsy associated with developmental impairment that may be due to either the underlying etiology or the superimposed epileptic activity, or both. "A PIEZO2 variant—associated with Marden–Walker syndrome—was found in a child with Early Infantile Developmental and Epileptic Encephalopathy." (PMID 41153369, 2025).
diabetes (1 paper, 2025). "Moreover, innocuous stimuli that induce mechanical allodynia are often part of diabetes-associated nerve damage, and the involvement of mechanosensitive Piezo2 has been implicated in this mechanism." (PMID 40137805, 2025).
dilated cardiomyopathy (1 paper, 2023). Cardiomyopathy which is characterized by dilation and contractile dysfunction of the left and right ventricles. "In the human diseased hearts, the RNA-sequencing data from human failing hearts with dilated cardiomyopathy (DCM) (GEO accession no: GSE29819) showed that the mRNA level of Piezo1 was up-regulated in the failing heart, while Piezo2 expression and other key ion channels remained unchanged." (PMID 37303604, 2023).
dry-eye (1 paper, 2025). "Piezo2 channels, expressed in mechanonociceptors and polymodal nociceptors, may undergo micro-injuries in dry-eye or neuropathic pain, becoming “leaky” and disrupting normal neuronal signaling, contributing to maladaptive sensitization and persistent pain." (PMID 40940733, 2025).
Duchenne muscular dystrophy (1 paper, 2024). Duchenne muscular dystrophy (DMD) is a neuromuscular disease characterized by rapidly progressive muscle weakness and wasting due to degeneration of skeletal, smooth and cardiac muscle. "GsMTx4 is an inhibitor of Piezo1 and Piezo2 and has been used to treat Duchenne muscular dystrophy." (PMID 39104594, 2024).